HAS3 (hyaluronan synthase 3)
Diseases named in the same sentence as HAS3 in open-access papers (continued):
Sharing a sentence is not in itself a finding about the gene and the disease.
myocardial ischemia (1 paper, 2025). A disorder of cardiac function caused by insufficient blood flow to the muscle tissue of the heart. "Similar to findings in T cells after myocardial ischemia/reperfusion (I/R), monocytes isolated from Has3-deficient mice with AAA displayed reduced CD44 surface expression and impaired migration across an endothelial layer." (PMID 41280888, 2025).
oncocytoma (1 paper, 2022). "In a clinical cohort of 129 tissues, HAS3 transcript levels were elevated in ccRCC and non-ccRCC specimens compared to NK and oncocytoma specimens." (PMID 36581895, 2022).
osteoarthritis (1 paper, 2019). A noninflammatory degenerative joint disease occurring chiefly in older persons, characterized by degeneration of the articular cartilage, hypertrophy of bone at the margins and changes in the synovial membrane. "A high expression of HAS3 was observed in the synovium of RA patients as well as in other inflammatory arthritis diseases, but rarely in osteoarthritis." (PMID 31260471, 2019).
rectum adenocarcinoma (1 paper, 2023). An adenocarcinoma arising from the rectum. "HAS3 was significantly positively correlated with MSI in three types of tumors, namely UCEC, LUSC, KICH; and significantly negatively correlated with MSI in seven types of tumors, namely GBMLGG, ESCA, STES, KIPAN, STAD, rectum adenocarcinoma (READ), DLBC." (PMID 37636435, 2023).
skin aging (1 paper, 2022). The gradual irreversible changes in structure of skin that occur as a result of the passage of time.. "In order to develop effective natural materials that can prevent skin aging, new materials were sought through in vitro evaluation focusing on AQP3, HAS3, and MMP-1 mechanisms." (PMID 36250021, 2022).
Stroke (1 paper, 2024). Sudden impairment of blood flow to a part of the brain due to occlusion or rupture of an artery to the brain. "The results showed that 6 genes filtered with optimal lambda value were identified as diagnostic characteristic genes in stroke, namely, HAS3, VIM, ZFP36L2, CPQ, F5, and PIK3CG." (PMID 38649659, 2024). "After taking the intersection of SCFA metabolism-related genes and the co-expression WGCNA modules of stroke, 10 SCFA-related hub genes were obtained, and 6 of them showed high diagnostic efficacy through LASSO regression and ROC analysis, including HAS3, VIM, ZFP36L2, CPQ, F5, and PIK3CG." (PMID 38649659, 2024).
synovitis (1 paper, 2021). Inflammation of a synovial membrane. "At 12 h post-induction of synovitis, both HA synthase 1 (HAS1) (p = 0.024) and HA synthase 3 (HAS3) (p = 0.01) expression were decreased in the cell pellets of the synovitis MCJ as compared to the lavage TCJ." (PMID 33980227, 2021).
temporal lobe epilepsy (1 paper, 2015). A localization-related (focal) form of epilepsy characterized by recurrent seizures that arise from foci within the temporal lobe, most commonly from its mesial aspect. "Interestingly, HA and HAS3 both decrease in perineuronal nets in the hippocampus following seizures in a rodent model of temporal lobe epilepsy while Has3-null mice have reduced hippocampal volumes and develop epileptic seizures." (PMID 26448752, 2015).
Thrombocytopenia (1 paper, 2025). A reduction in the number of circulating thrombocytes. "Megakaryocytes (MKs), the platelet progenitor cell, express only HAS2 and HAS3, and dysregulated metabolism of HA by MKs leads to thrombocytopenia." (PMID 41586377, 2025).
tumor (52 papers, 2008 to 2025). "Elevated HA accumulation was associated with a small growth advantage in the 4T1/HAS3 tumours compared to parental 4T1 tumours." (PMID 37081807, 2023). "Comparative Cox multivariate analyses by N stage and tumor histology showed asignificant association between poor survival and high pre-neoplastic cell HAS-3 levels(HR=1.19; P=0.04)." (PMID 26352698, 2015). "HAS3 overexpression led to increased accumulation of extracellular hyaluronan that was associated with faster tumor growth and enhanced response to PEGPH20." (PMID 25147816, 2014). "However, other studies reported that HAS3 that was associated with tumor progression, downregulate in early tumor development." (PMID 32708202, 2020). "Systemic inhibition of HA-synthesis and knockdown of tumour cell HAS3 cause decreased ESCC progression accompanied by tumour stroma remodelling and may therefore be used in novel approaches to ESCC therapy." (PMID 21429221, 2011). "After knock down of HAS3 xenografted OSC1 cells still exhibited strong pericellular HA staining concomitant with pronounced CD44 staining suggesting that the elevated CD44 expression may cause binding of stroma derived HA to the tumour cell surface." (PMID 21429221, 2011). "HAS3 and consequently, HA which promote tumor growth and metastasis, is the major target of Sorafenib in mRCC." (PMID 38726221, 2024). "For example, HAS3 expression is significantly increased in certain cancers, which contributes to the metastatic potential of tumor cells." (PMID 39766274, 2024). "Previous works by this group and others showed that HAS3 and related molecules are highly elevated in genitourinary tumors and promote tumor growth, angiogenesis, metastasis, and treatment-induced resistance." (PMID 38726221, 2024). "The study further showed that HAS3 levels are not only elevated in tumor tissues compared to the adjacent normal kidney tissues, but the levels potentially are independent prognostic indicators of metastasis and patient survival." (PMID 38726221, 2024). "Similar to normal mammary glands, CD45-/CD90.2 + fibroblasts specifically expressed Has1 whereas EpCAM + epithelial cells expressed elevated levels of Has3 in the HC11/R1-LM tumor model." (PMID 36723776, 2023). "Saline control MDA‐MB‐231 LM2‐4 tumours contained significantly less collagen than 4T1 (P = 0.003) and 4T1/HAS3 (P = 0.02) tumours." (PMID 37081807, 2023). "As binding between CD44 and HA plays a key role in the migration of BMSCs, the hyaluronic acid synthase-3 (HAS3) expression was compared among the various tumor cells." (PMID 37370133, 2023). "In comparison to the EV tumors, where the combination inhibited tumor growth by > 70%, ectopic-HAS3-expressing Caki-1 tumors (established by implanting HAS3 transfectants) were resistant to the treatment." (PMID 36581895, 2022). "In tumor specimens of patients who had or developed mRCC, HAS3 transcript levels were about 8–tenfold elevated compared to those who did not develop mRCC during follow-up." (PMID 36581895, 2022). "If the cytotoxic effects of SF are because it downregulates HAS3 and consequently inhibits the tumor-promoting effects of HA, then the ectopic expression of HAS3 under a viral promoter in RCC cells should make them resistant to the SF + MU combination." (PMID 36581895, 2022). "In RCC models, the combination inhibited tumor growth and metastasis with little toxicity; however, ectopic-HAS3-expressing tumors were resistant." (PMID 36581895, 2022). "The effect of PEGPH20 pre-treatment on PTX antitumor activity was assessed in parental and HAS3-overexpressing SKOV3 tumours." (PMID 34507591, 2021). "We found that the mRNA expression of HAS3 was detected at a higher level (22-fold) significantly in the normal tissues of paired tumor samples within the N > T group (p < 0.0001)." (PMID 34770956, 2021).
tumor (continued). "Among the N > T group, 10-fold higher HAS3 mRNA expression was detected preferentially (142/250, 56.8%) in normal tissues compared with tumor tissues of paired samples (blue bar 4)." (PMID 34770956, 2021). "The inhibition of HAS3 protein expression significantly increased tumor growth than the scrambled control sequence treated cells." (PMID 34770956, 2021). "Overexpression of miR-10b-5p has been shown to inhibit HAS3 expression, a hyaluronan synthase that can inhibit tumour growth." (PMID 32612164, 2020). "To validate the protein expression levels, we homogenized tissue from each tumor, and HAS3 and both differentiation markers in the N2a‐allografted tumors were analyzed via immunoblotting." (PMID 31274246, 2019). "Overexpression of HAS2 and HAS3 has been used to model HA-accumulating tumors and was shown to increase tumor growth." (PMID 31762938, 2019). "In HNSCC tumours, p63 expression is positively correlated with that of HAS3 and CD44, and the expression of three tumour‐related CD44 variants is associated with HNSCC progression in clinical samples." (PMID 30845357, 2019). "To understand the role of stromal hyaluronan in tumor progression, we engineered 3T3HAS3, a hyaluronan-producing fibroblast cell line, by lentiviral transduction of Balb/c 3T3 cells with the human hyaluronan synthase 3(HAS3) gene." (PMID 31762938, 2019). "Serial tumor tissue sections were taken, and HAS3, differentiation markers (GFAP and TUBB3), and an autophagic marker (LC3) were detected by IHC." (PMID 31274246, 2019). "The IHC data demonstrated that HAS3 was induced by melatonin treatment in a dose‐dependent manner in N2a‐allografted tumor tissue." (PMID 31274246, 2019). "High HAS3 expression correlates with tumor aggressiveness, whereas low molecular weight HA affects adhesion and catcher activity of the matrix." (PMID 27419629, 2016). "These microvilli, which can spontaneously break away from the tumor cells, retain the HAS3 enzyme and are coated in HA." (PMID 26380222, 2015). "Recently, Tammi and colleagues described the formation of tumor cell membrane protrusions that accompany the overexpression of HAS3, one of three enzymes that synthesize and secrete HA." (PMID 26380222, 2015). "Comparative Cox multivariateanalysis controlled by N stage and histologic tumor type showed that patients withhigh HAS-3 expression in pre-neoplastic cells obtained by lung/bronchial biopsypresented a significantly higher risk of death (HR=1.19; P=0.04)." (PMID 26352698, 2015). "Evidence from in vitro studies suggests that high expression of HAS3 induces abundant cell surface microvilli, which vastly increases the surface area of the tumor cell." (PMID 26380222, 2015). "Regulation and possible differential mechanisms of HAS2- and HAS3-mediated tumor growth are not completely understood." (PMID 25147816, 2014). "PEGPH20 depletes extracellular hyaluronan and leads to strong inhibition of tumor growth in HAS3-overexpressing tumors." (PMID 25147816, 2014). "Again HAS3v1 mRNA expression levels were strongly upregulated in G1 compared to control but decreased with higher tumor grading (HAS3, 10.91 fold of control in low grade versus 3.93 fold in high grade findings, p<0.001)." (PMID 24069434, 2013). "Of note, a steeper correlation between HAS3 and EGFR levels was found in the subgroup of T = 1 tumours, which possibly suggests a stronger dependence of this early tumour stage on EGF stimulated HAS3 expression." (PMID 21429221, 2011). "Specifically, it is proposed that ESCC tumour cells overexpress HAS3 in an EGFR dependent manner and that this overexpression supports a dedifferentiated proliferative tumour cell phenotype." (PMID 21429221, 2011). "In combination, tumour cell specific knock down of HAS3 pheno-copied the effect of systemic inhibition of HA synthesis." (PMID 21429221, 2011).
tumor (continued). "Immunohistochemical stainings of HAS proteins showed a low level of HAS1, a slightly elevated level of HAS3 in the tumor epithelia, and a variable elevation of HAS2 immunostaining in the tumor epithelial cells, in agreement with the mRNA assays." (PMID 19435493, 2009). "Similarly, high expression of HAS1 and HAS3 either tumor tissue or tumor stroma predicts poor prognosis or malignant progression in breast cancer, lung cancer, bladder cancer, and also chondrosarcoma." (PMID 36698043, 2023). "Other ECM components such as small-size hyaluronan synthase-3 (HAS-3) have been linked to malignant processes in a variety of carcinomas, while isoform HAS-2 downregulation has shown cisplatin resensitization and tumor growth arrest in OSCCs." (PMID 35159370, 2022). "To further confirm this hypothesis, we established HAS3 gene knockout (C57B6/J-Has3-KO) mice to generate a low HA in the tumor microenvironment." (PMID 34770956, 2021). "To test whether HAS3 encompassed in cutaneous tissue directly influences tumor growth, we established TNBC-PDX (F4, n = 6) mouse models." (PMID 34770956, 2021). "To test the opposite phenomena observed in MDAMB231 cells, we further test whether overexpression of the HAS3 protein inhibits tumor cell growth." (PMID 34770956, 2021). "However, in the T > N group, HAS3 mRNA expression in most tumor tissues was less than 10-fold than in the paired normal tissues (yellow bars 1–3)." (PMID 34770956, 2021). "Our study first explores the antitumor effects of HAS3 in tumor-adjacent ECM." (PMID 34770956, 2021). "Importantly, HAS3 enzyme produces HA of low (LMW) or middle (MMW) and is associated with metastasic behavior in some tumor cell lines." (PMID 32610620, 2020). "Ectopic HAS3 promoted OC-2 tumor volume and weights compared to vector control." (PMID 28107185, 2017). "Although HAS2 is the most studied synthase involved in embryonic and cardiac cushion morphogenesis and can stimulate cell proliferation and angiogenesis, HAS3 is the most active in the synthesis of short chain HA (100~1000 kDa) and highly expressed in tumor cells." (PMID 28107185, 2017). "However, in other cancer cells, e.g. oesophageal squamous cell carcinoma cells HAS3, promotes tumor growth as shown by HAS3 knock-down or application of the HAS-inhibitor 4-MU." (PMID 24069434, 2013). "Lentiviral knockdown of HAS3 in human ESCC cells prior to xenografting mimicked all effects of 4-MU treatment suggesting that hyaluronan produced by ESCC is accountable for major changes in tumour environment in vivo." (PMID 21429221, 2011). "HAS3 was the main isoform of the studied ESCC tumour samples." (PMID 21429221, 2011). "The effects on tumour progression and morphology of 4-methylumbelliferone (4-MU), an inhibitor of HA-synthesis, and of lentiviral knock down of HA-synthase 3 (HAS3), the main HAS isoform in the human ESCC tissues and the human ESCC cell line used in this study, were determined." (PMID 21429221, 2011). "This might indicate a stronger dependence of early tumour grades on EGF pathway signalling to maintain HAS3 activity." (PMID 21429221, 2011). "The lentiviral knockdown of HAS3 in the xenografted OSC1 cells resulted in reduced stromal HA staining and in addition in pronounced association of the residual HA with the circumference of tumour cell clusters." (PMID 21429221, 2011). "The recruitment of stromal HA in response to knock down of HAS3 by tumour cells might be part of a compensatory mechanism." (PMID 21429221, 2011). "However, this is the first demonstration that inhibition of a specific HAS isoform, HAS3, in tumour cells is as efficient as systemic HAS-inhibition by 4-MU." (PMID 21429221, 2011). "An analysis including both normal and different tumor specimens indicated that the proportion (%) of the HAS3-positive cells of all epithelial cells correlated with hyaluronan staining in the stroma (r = 0.424, p = 0.008), and negatively with HYAL1 mRNA (r = -0.438, p = 0.005)." (PMID 19435493, 2009).
tumor (continued). "Thus, the higher expression of HAS3 in these systems may reflect its role in more dynamic cellular processes, such as tumor progression and metastasis." (PMID 39766274, 2024). "Therefore, another possible explanation for the association of low HAS3 expression with a more favorable outcome may be that HAS3 is elevated in early tumor stages and HA synthesis is taken over by HAS1 and HAS2 during progression." (PMID 24069434, 2013). "Furthermore changes in tumour morphology and distribution of HA and HA receptors, following either systemic HA inhibition by 4-MU or inhibition of tumour HA production by lentiviral knockdown of HAS3, were examined." (PMID 21429221, 2011). "Because the systemic application of 4-MU inhibits HA synthesis in both tumour cells and stromal fibroblasts independently of the involved HAS isoforms, the relative contribution and functional significance of HA derived specifically from tumour cell associated HAS3 was addressed." (PMID 21429221, 2011). "Functionally, the HA/CD44 interactions might contribute to tumour cell proliferation, because after inhibition of HA synthesis by 4-MU or application of shRNA targeting HAS3 the remaining proliferative activity of tumour cells was confined to the CD44 positive tumour cell - stroma interface." (PMID 21429221, 2011). "It is likely that HAS1 and HAS3 act cooperatively with HAS2 to support HA deposition and tumor growth." (PMID 39946200, 2025). "HA production was also evaluated by immunohistochemistry analysis of HAS1, HAS2, HAS3, HYAL1, and HYAL2 expression on tumor cells." (PMID 39858106, 2025). "HAS1 expression was significantly higher in the tumor stage compared to the patch stage, whereas expression of HAS2 and HAS3 was moderate to strong in all disease stages." (PMID 39858106, 2025). "Decreases in HAS3 and CEMIP expression were also confirmed, suggesting a reduction in LMWHA production by tumor cells." (PMID 39858106, 2025). "We first analyzed HA synthases HAS1, HAS2, and HAS3, hyaluronidases HYAL1 and HYAL2, ABCC5 transporter, and CD44 expression in tumor tissue (TT) in TCGA database." (PMID 39039104, 2024). "This study explored the anti-migratory effects of HAS3 protein and its enzymatic product, HA, in the ECM surrounding tumor tissues." (PMID 34770956, 2021). "In this study, we first demonstrated that the mRNA and protein level of HAS3 were higher in normal breast epithelial cells (MCF-10A, MCF-12A, and 184A1) and adjacent normal stroma in corresponding tumor tissues." (PMID 34770956, 2021). "It is well known that members of the family of molecules of the HA signaling pathway, like HA synthases (HAS1, HAS2, HAS3), HA receptors and hyaluronidases (mainly HYAL1) are critical determinants of tumor growth and progression." (PMID 32610620, 2020). "On the other hand, several members of the HA signaling pathway, like HA synthases (HAS1, HAS2, HAS3), HA receptors and hyaluronidases (mainly HYAL1) are critical determinants of growth and progression of the tumor." (PMID 32610620, 2020). "Several genes, such as TMPRSS4, STAR, ST7L, HAS3, FGFR3, CASZ1 and HR, were found to have gene expression changes at the very earliest stages of tumor thickening." (PMID 18442402, 2008). "Some types of cancer cells express hyaluronan synthases (HAS1, HAS2, and HAS3), as well as fibroblasts and chondrocytes as part of the extracellular matrix, and the signaling between HA and CD44 is deemed critical for tumor proliferation and the spread of cancer." (PMID 40011711, 2025). "Importantly, our data indicate that bexarotene reduces LMWHA and HMWHA accumulation by suppressing the expression of HAS1, HAS3, and CEMIP in tumor cells and HAS1 and HAS2 in fibroblasts." (PMID 39858106, 2025). "Moreover, the reduction of HAS3, ABCC5, and SOX2 gene expression induced by Pa + 4Mu, previously observed in vitro, was confirmed in tumor tissue from treated mice." (PMID 39039104, 2024).